LGI1 (leucine rich glioma inactivated 1)
Diseases named in the same sentence as LGI1 in open-access papers (continued):
Sharing a sentence is not in itself a finding about the gene and the disease.
sensorineural hearing loss (1 paper, 2025). "Auditory symptoms, particularly sensorineural hearing loss (SNHL), are uncommon but may occur due to LGI-1 expression in auditory pathways." (PMID 40904981, 2025).
squamous cell carcinoma (1 paper, 2019). A carcinoma arising from squamous epithelial cells. "Interestingly, several DM protein-coding genes, namely the LGI1, IRF2, and NRG1 genes, have been implicated in squamous cell carcinoma, which involves the same keratinocyte layer that is exclusively hijacked by HPV infection." (PMID 31892232, 2019).
teratoma (1 paper, 2021). A non-seminomatous germ cell tumor characterized by the presence of various tissues which correspond to the different germinal layers (endoderm, mesoderm, and ectoderm). "The median CSF-NfL concentration at diagnosis in LGI1-AE patients (n=16) was higher than in idiopathic/teratoma associated NMDAR-AE (n=27) (1178.5 pg/mL vs 284 pg/mL, p<0.0001)." (PMID 34975832, 2021). "In conclusion, CSF-NfL levels at diagnosis were higher in LGI1-AE patients than in idiopathic and teratoma associated NMDAR-AE and our data indicate that high CSF-NfL may relate to worse long-term outcome." (PMID 34975832, 2021). "Our study suggests that idiopathic and teratoma induced NMDAR-AE patients have lower CSF-NfL levels than patients with LGI1-AE at disease onset." (PMID 34975832, 2021). "CSF-NfL levels declined in the majority of idiopathic/teratoma associated NMDAR-AE patients within 3 to 9 months after diagnosis, whereas CSF-NfL levels during follow-up in LGI1-AE patients were more heterogenous." (PMID 34975832, 2021). "Secondary NMDAR-AE patients were more often male, middle-aged, more frequently had an abnormal MRI and had a worse outcome at final follow-up, when compared to idiopathic/teratoma associated NMDAR-AE and LGI1-AE patients." (PMID 34975832, 2021). "Applying age adjusted cut-off values for CSF-NfL elevation revealed that only five idiopathic/teratoma associated NMDAR-AE patients (19%) had elevated CSF-NfL at diagnosis, compared to 50% of LGI1-AE patients (p=0.04)." (PMID 34975832, 2021). "When applying age related cut offs for CSF-NfL and evaluating the entire AE cohort and the idiopathic/teratoma associated NMDAR- and LGI1-AE combined, an association between elevated CSF-NfL at diagnosis and a poor outcome was found (p=0.0009 and p=0.006)." (PMID 34975832, 2021). "Twelve idiopathic/teratoma associated NMDAR-AE and nine LGI1-AE patients had CSF available for NfL measurement during follow-up." (PMID 34975832, 2021). "A higher CSF-NfL level at diagnosis was associated with a higher mRS score at final follow-up in both idiopathic/teratoma associated NMDAR-AE and LGI1-AE (p=0.001 and p=0.04)." (PMID 34975832, 2021).
transverse myelitis (1 paper, 2013). "In one patient with isolated longitudinally extensive transverse myelitis, the IHC-o identified LGI1 antibodies instead of NMO-IgG; the identity of LGI1 was subsequently confirmed with the appropriate CBA." (PMID 24223884, 2013).
Vocal cord paralysis (1 paper, 2024). A loss of the ability to move the vocal folds. "Given the absence of an inciting event or identifiable risk factor, his bilateral vocal cord paralysis was attributed to anti-LGI1 LE." (PMID 39664290, 2024).
tumor (45 papers, 2008 to 2025). "LGI1‐positive patients rarely have a combination of tumor and the prevalence is at ~10%,72 which seems inconsistent with the findings of this paper." (PMID 36914970, 2023). "Altogether, there are strong indications that LGI1 is a tumor suppressor gene, although some studies debate this." (PMID 36289737, 2022). "We report the clinical characteristics of a Chinese MoS patient with only LGI1-antibody seropositivity, and further support the view that non-neoplasm MoS patients respond well to immunotherapy." (PMID 33941099, 2021). "LGI1 substantially reduced local tumour growth (mean 450 mm3 versus 150 mm3), in a similar manner to that observed with the LY2-ADAM22 KO cells." (PMID 33208158, 2020). "Taken together, these in vitro and ex vivo studies suggest LGI1 peptide mimetic as an ADAM22-specific therapeutic with anti-tumour potential." (PMID 33208158, 2020). "However, LGI1 is more often expressed in tumor tissues of adult-type diffuse glioma patients with epilepsy than without epilepsy." (PMID 36289737, 2022). "Unlike some AE forms (typically Group II), LGI1 AE is not commonly associated with neoplasms and responds well to immunotherapy, where studies have shown that 67% of patients can achieve favorable outcomes." (PMID 35979060, 2022). "Because of the dual role of LGI1 as both an anti-epileptogenic and tumor-suppressive protein that inhibits MMP expression, LGI1 could be an excellent therapeutic target for epileptic tumors in general and LEATs specifically." (PMID 36289737, 2022). "Because different autoantibodies may indicate different tumor types, furthermore, responses to treatment and long-term outcome seem to be different between LGI1 and anti-NMDA receptor encephalitis." (PMID 29110638, 2017). "The lethal effect produced by LGI1 expression in HeLa cells suggests that the proposed role of tumor suppressor might be extended to adenocarcinoma-derived cells." (PMID 20111625, 2009). "Because of this LGI1 was proposed to be a tumor suppressor gene." (PMID 18578868, 2008). "The antibodies are much less frequently associated with tumours, and are directed against extracellular epitopes on surface antigens strongly expressed within the CNS, such as the N-methyl-d-aspartate receptor (NMDAR) and leucine-rich glioma-inactivated 1 (LGI1)." (PMID 25491076, 2015). "Besides its anti-epileptogenic effects, LGI1 is also hypothesized to be a tumor suppressor gene." (PMID 36289737, 2022). "As strong tumor suppressors and brain-specific secretory proteins, both OPCML and LGI1 are worth further investigation in GBM, and the strong binding affinity with TMZ observed in the present work indicates their potential as novel targets for TMZ." (PMID 36364024, 2022). "Seemingly paradoxically, α2β1 expression also increased the mRNA levels of two tumor suppressors, namely SCARA5 (Scavenger receptor class A, member 5) and LGI1 (Leucine-rich, glioma inactivated 1)." (PMID 30197754, 2018). "After combining the results of auxiliary examinations, the final diagnosis of AE was made, and the serum and cerebrospinal fluid were positive for anti-LGI1 and anti-mGluR2 antibodies, and the screening of the tumor was negative." (PMID 40519939, 2025). "LGI1 is mainly a non-malignant tumor and thought to be responsive to immunotherapy." (PMID 33162923, 2020). "Finally, from the nine LGI1- and four CASPR2-antibody patients with a tumour, there were no significant HLA differences compared to non-tumour patients." (PMID 29788256, 2018).
movement disorder (17 papers, 2018 to 2025). Neurological conditions resulting in abnormal voluntary or involuntary movement, which may impact the speed, fluency, quality and ease of movement. "For example, the constellation of psychiatric features and the multi-faceted movement disorder observed in patients with NMDAR antibodies are highly distinctive, as are the faciobrachial dystonic seizures observed in close association with LGI1 antibodies." (PMID 31655889, 2021). "At least one kind of movement disorder was present in 40% of the entire AE cohort, 53% with anti-NMDA receptor antibodies, 33% with anti-CASPR2 antibodies, 30% with anti-LGI1 antibodies and 13% with anti-GABA receptor antibodies." (PMID 37545714, 2023). "Hence, this study suggests that abnormalities of the BG might be involved in the etiology of FBDS and further supports the hypothesis that LGI1-associated FBDS is more likely a form of movement disorder rather than an epileptic disease in nature." (PMID 32581996, 2020).
neurological diseases (16 papers, 2016 to 2025). "The phenotype of anti-LGI1 Ab-associated neurological diseases is mainly encephalitis whereas anti-Caspr2 Ab-associated neurological diseases are more diverse and include CAs." (PMID 32668612, 2020). "This is a unique presentation in that although laryngeal involvement is seen in autoimmune encephalitides and neurological diseases vocal cord failure secondary to anti-LGI1 LE has yet to be documented." (PMID 39664290, 2024). "LGI1 and CASPR2 double-positive antibodies associated with the neurological diseases can occur in children of all ages and involve multiple nervous systems." (PMID 35463890, 2022). "This study aimed to investigate and summarize the clinical features and long-term prognosis of children’s LGI1 and CASPR2 antibodies related to neurological disorders." (PMID 35463890, 2022). "While the involvement of the larynx is seen in various other autoimmune and neurological diseases, it is not a known issue with anti-LGI1 LE." (PMID 39664290, 2024). "Within this population of 32 dogs with neurologic disease and 1 healthy control, antibodies were not identified against AMPAR1/R2 or GABABR1/R2 or CASPR2, LGI1, and DPPX in any dog." (PMID 31495976, 2019).
cancer (14 papers, 2009 to 2024). A tumor composed of atypical neoplastic, often pleomorphic cells that invade other tissues. "In this study we performed stable LGI1 expression in HeLa cells to examine whether the noxious effect of LGI1 might be extended to cancer cells of diverse origin." (PMID 20111625, 2009). "Approximately 10% of LGI1 antibody encephalitis cases are associated with various cancers, such as thymoma, and approximately half of GABAB receptor antibody encephalitis cases are associated with small-cell lung cancer, which is a common cause of death from cancer." (PMID 37592180, 2023). "However, the rest of the genes (LGI1, PCSK2, CTNND2, SLC6A19, DAO, TMEM82 and CPNE7) could be related to CRC and have been previously identified in other types of cancer." (PMID 30940089, 2019).
psychiatric disorder (10 papers, 2016 to 2025). A disorder characterized by behavioral and/or psychological abnormalities, often accompanied by physical symptoms. "However, rare variants present less frequently in EVS database than in the disease cohort suggest that there could be rare LGI1 variants in subjects with psychiatric diseases." (PMID 27468420, 2016). "The expressions of GABAARγ2, GAD65, LGI1, SCN1β, and GFAP were significantly higher in the hippocampus of epileptic subjects with psychiatric disorders compared to patients without psychiatric disorders (P ≤ 0.05)." (PMID 37658249, 2024).
adenocarcinoma (2 papers, 2009 to 2025). A common cancer characterized by the presence of malignant glandular cells. "The results suggested that LGI1 is capable to restrain growth and survival of adenocarcinoma cells such as HeLa." (PMID 20111625, 2009).
infection (2 papers, 2024 to 2025). The state of being infected such as from the introduction of a foreign agent such as serum, vaccine, antigenic substance or organism. "The two patients in this study developed the condition following infection, and tests for NMDAR, CASPR2, LGI1, AMPA, GABA, DPPX, mGluR, GAD65, MOG, GFAP, and AQP4 antibodies were all negative." (PMID 38765268, 2024).
infectious disease (1 paper, 2025). A disorder directly resulting from the presence and activity of a microbial, viral, or parasitic agent in humans. "Serology for infectious diseases, including Toxoplasma gondii, FeLV and FIV, as well as for autoimmune limbic encephalitis (feline anit-LGI1 antibodies) was negative." (PMID 40251393, 2025).
overlap syndrome (1 paper, 2024). "Both domestic and international reports have documented cases of anti-IgLON5 antibody overlap syndrome with LGI1 antibodies." (PMID 38765268, 2024).
retinopathy (1 paper, 2023). "In some of these cases, additional antibodies were pathogenically relevant, resulting a complex clinical pictures (e.g., Recoverin antibodies and retinopathy, MOG antibodies and cerebral cortical encephalitis, and LGI1 antibodies and faciobrachial dystonic seizures)." (PMID 37025999, 2023).
LGI1 also shares sentences with these, for which no sentence is quoted: autonomic dysfunction (6 papers); dysautonomia (6); cognitive disorder (4); small cell lung carcinoma (4); cerebellar ataxia (3); Creutzfeldt-Jakob disease (3); Hashimoto's encephalopathy (3); nephrotic syndrome (3); ovarian teratoma (3); prostate carcinoma (3); Stroke (3); acute disseminated encephalomyelitis (2); autism (2); autoimmune neurological diseases (2); complex partial seizures (2); demyelinating disease (2); developmental delay (2); Dystonia (2); focal epilepsy (2); frontotemporal dementia (2); hypersomnia (2); Intellectual disability (2); Malignant thymoma (2); membranous nephropathy (2); mental disorder (2); mood changes (2); neurodegenerative disease (2); orthostatic hypotension (2); psoriasis (2); Sjögren's syndrome (2).
A further 83 diseases each share a sentence with LGI1 in 2 papers or fewer.